EGFR (epidermal growth factor receptor)
Diseases named in the same sentence as EGFR in open-access papers (continued):
Sharing a sentence is not in itself a finding about the gene and the disease.
cancer (continued). "B1SP is a multi‐RTK pathway inhibitor targeting EGFR, MET, and HER2/ErbB2 and has potential clinical utility for a number of cancers wherein these RTKs are clinically validated targets including lung, breast, and colorectal cancers." (PMID 29348142, 2018). "The substitution of threonine with methionine at amino acid position 790 (T790M), which reduces the ability of ATP-competitive reversible EGFR-TKI binding to EGFR tyrosine kinase domain, results in cancer cells resistant to gefitinib and erlotinib." (PMID 29713646, 2018). "EGFR-mediated entry of HIV-positive exosomes into target cancer cells is a necessary step for subsequent activation of ERK1/2, a process that involves EGFR and TLR3." (PMID 30389917, 2018). "Our results suggest that upon ligand stimulation, AR increases EGFR expression, which in turn acts on AKT pathways to promote cancer cell survival and invasiveness." (PMID 30134822, 2018). "We show here that Fas in its pro-survival state, phosphorylated at Y291 (pY291-Fas), functionally interacts with the epidermal growth factor receptor (EGFR), a key cancer-driving protein and major therapeutic target." (PMID 30127519, 2018). "The involvement of EGFR/ErbB2 receptors and the PI3K/Akt pathway in the regulation of SOCE was confirmed in other cell lines derived from various cancer types." (PMID 29662626, 2018). "In several types of cancer, HER3 functions as a tumorigenic molecule via interactions with HER2 and EGFR." (PMID 30404198, 2018). "According to these findings in our experiments, cancer cells being in the state of EMT induced by nuclear translocation of PKM2, which is specifically activated by EGFR signaling, was essential for cancer cell progression." (PMID 30333907, 2018). "miR-140-3p targets EGFR and IGF1R, which leads to the inactivation of the PI3K/AKT pathway which is involved in cancer cell survival and metabolism." (PMID 30559931, 2018). "For instance, EGFR activation by EGF induces endogenous production of intracellular reactive oxygen species (ROS) and H2O2 in cancer cell lines." (PMID 30595797, 2018). "uPA, TEM8 and EGFR overexpression and ERK1/2 phosphorylation were found co-located on frozen cancer tissue sections." (PMID 30241478, 2018). "Trastuzumab, an anti-ErbB2 antibody, and lapatinib, a small-molecule inhibitor of ErbB2/epidermal growth factor receptor (EGFR), are used for treatment of ErbB2-positive cancers." (PMID 30545388, 2018). "HER2 forms heterodimer with EGFR and triggers activation of key downstream signaling molecules involved in HER2-overexpressed cancer cell proliferation and survival." (PMID 29467385, 2018). "Caveolins can bind and regulate proteins with the CBD including NOS, MMP2, and epidermal growth factor receptor (EGFR), and they are involved in numerous cellular activities such as apoptosis, cholesterol transport, and cancer metastasis." (PMID 30572925, 2018). "Other reported immune escape mechanisms that can play a role because of constitutive or adaptive EGFR-signaling are the expression of PD-L1 and the inhibition of antigen processing via dephosphorylation of STAT1 in cancer cells." (PMID 30192802, 2018). "Anti-cancer drug-resistant cancer cell lines show an increased expression of phosphorylated epidermal growth factor receptor (pEGFRY845) and an interaction between CAGE and EGFR." (PMID 30583572, 2018). "For example, many growth factor receptors such as EGFR, VEGFR, ERBB2, which are amplified in cancers, can also generate a soluble decoy receptor by alternative splicing." (PMID 30329087, 2018). "Epidermal growth factor receptor (EGFR; also known as ErbB1 or Her1) is a receptor tyrosine kinase (RTK) that is involved in eukaryotic development and cancer pathogenesis." (PMID 29358589, 2018). "Genomic analysis has been used to uncover intratumor heterogeneity in terms of copy number alterations in EGFR and CDKN2A/B/p14ARF as early events, and aberrations in PDGFRA and PTEN as later events during progression of cancer." (PMID 30374421, 2018).
cancer (continued). "Thus, the ligand-activated GPER triggers the Epidermal Growth Factor Receptor (EGFR)/extracellular signal–regulated kinases(ERK)/PKC signaling transduction pathway generating a feed forward loop that couples IL-1β induction by CAF to IL-1R1 expression by cancer cells." (PMID 30042333, 2018). "In cancer cells, the transmembrane portion of MUC1 and EGFR physically interact, although in normal epithelial cells this interaction is prevented by their differential localization at the apical and basolateral cell side, respectively." (PMID 29462882, 2018). "With the advent of novel therapies targeting the epidermal growth factor receptor (EGFR), the focus once again shifted to KRAS as a predictor of response to cancer therapy." (PMID 30283732, 2018). "The selective EGFR L858R/T790M inhibition of YL143 was investigated in H1975, HCC827, A549, and A431 cancer cells harboring different statuses of EGFR by Western blotting analysis." (PMID 29532998, 2018). "Signalling through HER receptors—ie, EGFR, HER2, HER3, and HER4—and their downstream pathways is a key mechanism that promotes proliferation and the malignant phenotype in cancer." (PMID 29254887, 2018). "While Cortactin stimulates metastasis of cancer cells, CTNN alsos inhibit down-regulation of the EGFR and MET signaling pathways." (PMID 27903975, 2017). "Our data emphasized the pro-apoptotic and pro-inflammatory potential of drugs targeting the EGFR-ERK axis in the epidermis, with implications for their toxicity but also for activation of the anti-cancer defense in the skin." (PMID 29064427, 2017). "One panel of cancer cell lines with predetermined numbers of HER2 and EGFR molecules on the cell surface membrane were selected for cytotoxicity studies of the BsAb (CD3×HER2)." (PMID 28827777, 2017). "Cellular signaling was represented by pathways that drive proliferation in ER+ and ERBB2+ cancer cells (e.g., MAPK, EGFR/ERBB2 and estrogen signaling), and additional downstream pathways involved in proliferation, apoptosis and survival." (PMID 29269772, 2017). "It was reported that signaling molecules such as EGFR, Ras, PKC, AKT/PKB and mTOR, were found to play important roles in human cancer cells and were involved in cell proliferation, differentiation and survival." (PMID 29254483, 2017). "The cytotoxicity effect of ginkgetin was illustrated in three cancer cell lines, A549 (EGFR, PIK3CA, p52 functional), PC9 (EGFR mutant) and NCIH-460 (EGFR, p52 functional, PIK3CA mutant)." (PMID 29190983, 2017). "As the EGFR signaling pathway is frequently activated in TNBC, ADAM12-mediated increase of EGFR activity should be the most relevant in this type of cancer." (PMID 28148288, 2017). "The authors demonstrated enhanced cellular uptake of the nanogels in SKOV-3 cancer cells overexpressing both CD44 and EGFR." (PMID 29271876, 2017). "In this study, we demonstrated that EGFR triggered the formation of tumorspheres derived from HCC827 and A549 cells, which expressed CD133, Oct4, and Nanog used as the cancer stemness models." (PMID 28787001, 2017). "We next tested PLIMB by labeling epidermal growth factor receptor (EGFR), a protein with implications in many cancers, before and after binding one of its native ligands, epidermal growth factor (EGF)." (PMID 29021557, 2017). "Our previous studies focused on the use of chemical vectors to target polyIC to EGFR- and HER2-overexpressing cancer cells." (PMID 28445962, 2017). "Currently, cancer patients are eligible for adjuvant therapies targeting cell surface antigens such as HER2 and EGFR, primarily in late stages of disease, when metastases have already developed or tumors relapsed." (PMID 27683128, 2017).
cancer (continued). "In these studies, it was commonly found that HER2/EGFR/Akt signaling axis was activated by trametinib and that cotreatment with HER2 inhibitors synergizes the anticancer activity of trametinib in various cancer types." (PMID 28632938, 2017). "We plated the established (pure cancer cell) cell lines of EGFR mutant or ALK-translocated NSCLCs into 384-well plates and compared their sensitivity to an EGFR or ALK inhibitor, respectively, using CellTiter-Glo or the immunofluorescence-based method." (PMID 29241554, 2017). "In conclusion, self‐sustenance in cancer cells is based on a signaling synergy, individually balanced between GAS6 TAM‐dependent PDK‐RSK‐mTOR survival pathway and the AXLY779/EGFR/MET‐driven SRC‐mTOR pathway." (PMID 28675785, 2017). "Basal A, also called “basal” cancers (ER-, PR-, HER2-) have high Ki67 expression, typically express epidermal growth factor receptor (EGFR+) and/or cytokeratin 5/6, and frequently respond to chemotherapy." (PMID 28583138, 2017). "Deregulation of Epidermal Growth Factor Receptor (EGFR) signaling is involved in HNSCC pathogenesis by regulating cell survival, cancer stem cells (CSCs), and resistance to CRT." (PMID 28423495, 2017). "The PEG engager was designed to bind to EGFR on TNBC cells but remain dormant until contact and binding to PEG-coated nanocarriers induces rapid internalization into cancer cells." (PMID 28593948, 2017). "More specifically, the phosphorylation level of EGFR and Akt were decreased at higher cell density in these normal lung cells, which are opposite to HCT116 and CNE-2Z cancer cells." (PMID 28061454, 2017). "Taken together, these data indicated that TUSC3 inhibits EGFR phosphorylation and down-stream signaling in human CRC and non-cancer cells." (PMID 29156678, 2017). "We found that increased EGFR phosphorylation resulted in G9a upregulation in HCC827- and A549-derived tumorspheres to maintain cancer stemness." (PMID 28787001, 2017). "Transactivation of EGFR by COX-2-derived PGE2—thereby initiating a positive feedback loop between EGFR and COX-2 signaling—has been reported in some cancer types." (PMID 28978083, 2017). "c-MET/EGFR signaling is a strong stimulator for cancer proliferation and survival, and therefore, the miR-206-mediated dual repression of c-MET and EGFR can confer antitumor effects." (PMID 29291022, 2017). "Similarly, it is hypothesized that mutations in the tyrosine kinase domain of the epidermal growth factor receptor (EGFR) are responsible for the activation of the EGFR pathway, a common molecular feature of many cancers that is also observed in cell lines exposed to arsenic." (PMID 28179585, 2017). "CTTN promotes cancer cell mobility, and Timpson's research suggested CTTN inhibited EGFR ubiquitination and degradation in HNSCC." (PMID 27903975, 2017). "Nanobodies, such as those against EGFR, Her2, VEGFR2, c-Met, CXCR7 and MUC-1, targeting transmembrane proteins and extracellular tumor-specific glycoproteins for cancer therapy, can be coupled with effector domain like toxins." (PMID 28445134, 2017). "Western blot analysis showed that multiple components in the EGFR-Akt-mTOR pathway were clearly affected by cell density in both HCT116 and CNE-2Z cancer cell lines." (PMID 28061454, 2017). "This hub plays major roles in cancer cells due to its connections to critical pathways such as PLD, EGFR, and c-Met SPs30." (PMID 29062084, 2017). "Three drugs were found to exhibit anticancer activity in the cancer cells and two of them were more potent in NSCLC-harboring EGFR L858R/T790M than those with EGFR L858R." (PMID 29238696, 2017).
cancer (continued). "The epidermal growth factor receptor (EGFR/HER) kinase family is a regulator of cellular proliferation, differentiation, and survival, as well as being factors leading to cancer initiation, maintenance, and progression." (PMID 29410730, 2017). "These therapeutic mAbs bind to the extracellular domain of EGFR and inhibit downstream signaling of the RAS/MAPK and PI3K/AKT pathways, which promote (cancer) cell proliferation, survival and growth." (PMID 28199979, 2017). "Several malignant tumours have recently achieved personalized cancer treatment in clinical practice, such as anti-HER2 antibody for HER2-positive breast cancer, anti-EGFR therapy for KRAS wild-type colon cancer, and BRAF inhibitor for BRAF mutant melanoma." (PMID 28548943, 2017). "Aberrant activation of EGFR, HER2, c-MYC, or MET is considered to be a promising target for specific molecular treatments in various cancers, including CRC." (PMID 28764718, 2017). "To determine if the change of LINC00052 expression is HER3 specific, we treated cancer cells with lapatinib (a compound that inhibits kinase activity of HER2 and EGFR) or trastuzumab (a HER2-blocking antibody)." (PMID 28036286, 2017). "We therefore performed a matched-pair case-control study retrospectively to investigate the different efficacy of EGFR-TKI in EGFR-mutant SQC and ADC patients from 3 cancer centers." (PMID 28591695, 2017). "This investigation identifies a previously unrecognized mechanism, in which H3K23ac/TRIM24 functions as a mediator of EGFR/EGFRvIII activation of STAT3 signaling, thereby promoting tumorigenesis in human cancers." (PMID 29129908, 2017). "Here we demonstrate that DDAs activate the Unfolded Protein Response (UPR) and that this plays a role in their ability to kill EGFR+ and HER2+ cancer cells." (PMID 28423644, 2017). "TM-LA nanotags are also biocompatible and showed that it is possible to recognize cancer cells when further modified with antibodies specific for HER2 and EGFR cancer proteins." (PMID 28085088, 2017). "To dissect the relative contribution of each pathway to resistance against anti-EGFR therapy, we stably expressed a ΔRAF-1/ERTam- or a myristoylated-AKT/ERTam (myr-AKT/ERTam) construct in RAS wild type A431 and Difi cancer cell lines." (PMID 28507280, 2017). "Tumorspheres derived from epidermal growth factor receptor (EGFR)-mutant HCC827 and EGFR wild-type A549 cells expressing higher cancer stemness markers (CD133, Oct4, and Nanog) were used as cancer stemness models." (PMID 28787001, 2017). "Clinically ineffective IGF1R-directed therapies may be associated with the ability of the cancer cell to re-activate the signaling pathway in addition to alternative activation of downstream IGF1R signaling pathways by other growth-promoting receptors in the cell such as HER2/3, EGFR and InsR." (PMID 29207959, 2017). "Iressa (gefitinib) interrupts signaling through the epidermal growth factor receptor (EGFR) in target cells and has been used in the treatment of certain breast, lung, and other cancers." (PMID 28724435, 2017). "EGFR homodimers or heterodimers with other HER members, such as HER2 and HER3, activate downstream signaling cascades in many cancers." (PMID 28891752, 2017). "EGFR tyrosine kinase inhibitors (EGFR-TKI) induce autophagy and, in most cases, play a protective role in cancer cells." (PMID 28338617, 2017). "It is a tyrosine kinase inhibitor, which acts on the epidermal growth factor receptor (EGFR) and is the second targeted therapy against HBP cancers, along with sorafenib." (PMID 28106782, 2017). "The miR-145 is able to suppress cancer proliferation, invasion and metastases through suppression of mucin-1, RTKN, c-Myc, and EGFR." (PMID 28456786, 2017). "Recent studies implicate the endocytic adaptor protein Endo II in regulating EGFR signaling, invadopodia formation, trafficking of matrix metalloproteinase MT1-MMP, cancer stemness and metastasis." (PMID 28974266, 2017).
cancer (continued). "EGFR and VEGF are crucial signaling molecules which have been believed to promote cancer cell growth and metastasis." (PMID 28202050, 2017). "EGFR is activated by its ligands and then triggers activation of the Ras/Raf/MEK/ERK1/2 signalling pathway, which plays a critical role in cancer development." (PMID 28541302, 2017). "Engagement of EGFR by its ligand can activate the downstream ERK and PI3K/AKT signaling, which are crucial for the proliferation, migration and invasion of cancer cells." (PMID 29152147, 2017). "Dozens of eIF4E2 mRNA targets have strong ties to cancer such as a group of receptor tyrosine kinases including EGFR, platelet-derived growth factor receptor-alpha, insulin-like growth factor 1 receptor, and HER-2, which most cancers overexpress at least one." (PMID 29317983, 2017). "Some genetic alterations, including changes in EGFR and MET, were observed at relatively low frequencies, and these alterations were detected in less than 5% of cancers analysed in our study." (PMID 28764718, 2017). "The major pathways altered more prominently in ETS-positive cancers were the PI3K-AKT, EGFR, TGF-beta Receptor Complex, PDGF and FGFR signaling pathways." (PMID 28945760, 2017). "In contrast, targeted therapeutic agents, which block individual pathways that cancer cells are addicted to (such as EGFR, BRAF, MET or HER2 signaling), are specific for cancer cells and have potentially fewer side effects." (PMID 28420162, 2017). "In human cancer tissue, FOXD3 expression was reduced while EGFR/Ras/Raf/MEK/ERK signal pathway was activated." (PMID 27926503, 2017). "The inhibitory effects on EGFR (pEGFR –tyr1173) and AKT (pAKT Serine473) signaling, downregulates downstream pro-survival signaling (mTOR and NF-κB) in cancer cell lines." (PMID 29234489, 2017). "Tyrosine kinase inhibitors targeting the epidermal growth factor receptor (EGFR-TKIs) have been recently developed and appear to work effectively against several types of cancer, including NSCLC." (PMID 28489575, 2017). "The human epidermal growth factor receptor (HER1) and its partner HER2 are extensively described oncogenes and validated targets for cancer therapy." (PMID 29137309, 2017). "Epidermal growth factor receptor (EGFR) is an important regulator of epithelial cell growth and survival in normal and cancerous tissues and is a principal therapeutic target for cancer treatment." (PMID 28731466, 2017). "The aim of the study was to identify clinically used drug candidates for repurposing to treat EGFR TKI-resistant NSCLC by in silico docking simulation and to validate the chosen drug candidates in cancer cell models." (PMID 29238696, 2017). "EGFR mainly activates the RAS pathway, promotes cell proliferation and facilitates cancer progression." (PMID 26461472, 2017). "Nevertheless, we previously showed that the semi-automatic method that we used as a substitute, produced reliable results when we analyzed the effect of inhibitors or siRNA against EGFR, MMP3 or the Rho GTPases Rac1 and Rho in cancer cells." (PMID 29237412, 2017). "A number of studies have been conducted on resistance-related factors, such as overexpression of DNA repair proteins, abnormal expression of epidermal growth factor receptor (EGFR), autophagy, angiogenesis, and cancer stem cells." (PMID 28968954, 2017). "In these cancers, MiR-7 targets several proto-oncogenes, such as insulin receptor substrate 1 (IRS1), epidermal growth factor receptor (EGFR), and p21 protein (Cdc42/Rac)-activated kinase 1 (PAK1)." (PMID 28239300, 2017). "In vivo molecular imaging using radiolabelled Affibody molecules has been demonstrated in preclinical studies for several cancer-related molecular targets, e.g. HER2, EGFR, HER3, and IGF-1R." (PMID 28729680, 2017). "Collectively, our results demonstrated that the NRF2 silencing-inducible miR-206 targeted both c-MET and EGFR, and subsequently suppressed the BCRP level in cancer cells." (PMID 29291022, 2017).